UBE2U (ubiquitin conjugating enzyme E2 U)
Description:
Catalyzes the covalent attachment of ubiquitin to other proteins.
Synonyms: MGC35130
Tractability: PROTAC: UniProt records ubiquitination sites on it.
Gene: Protein-coding gene on chromosome 1 (64,203,623 to 64,267,368, forward strand). Ensembl gene ENSG00000177414.
Pathways (Reactome):
Immune System: Antigen processing: Ubiquitination & Proteasome degradation
Gene Ontology:
Molecular function: protein binding; ubiquitin conjugating enzyme activity; ubiquitin-like protein transferase activity
Biological process: DNA repair; proteasome-mediated ubiquitin-dependent protein catabolic process; protein polyubiquitination; protein modification by small protein conjugation; protein ubiquitination
Cellular component: HULC complex
Genetic constraint (gnomAD): Loss-of-function variants: 12 observed, 14.72 expected, observed/expected ratio (o/e) 0.82, 90% interval 0.52 to 1.32. The upper end of that interval is the gene's LOEUF score, 1.32, which puts it in group 5 of 6, group 1 being the genes least tolerant of losing a copy. Missense variants: 220 observed, 249.94 expected, observed/expected ratio (o/e) 0.88, 90% interval 0.79 to 0.98. Synonymous variants: 78 observed, 86.34 expected, observed/expected ratio (o/e) 0.9, 90% interval 0.75 to 1.09.
Homologues: Orthologues: chimpanzee UBE2U (97% identical), macaque UBE2U (92% identical), dog UBE2U (66% identical), rabbit UBE2U (63% identical), mouse Ube2u (49% identical), rat Ube2u (45% identical), tropical clawed frog ube2u (35% identical). Paralogues in human: CDC34 (17% identical), UBE2G1 (16% identical), UBE2R2 (16% identical), UBE2A (16% identical), UBE2N (15% identical), UBE2B (15% identical), UBE2C (15% identical), UBE2I (14% identical), UBE2K (14% identical), AKTIP (14% identical), UBE2S (14% identical), UBE2NL (13% identical), and 12 more.
Diseases named in the same sentence as UBE2U in open-access papers:
UBE2U is named in the same sentence as 10 diseases in open-access papers, as found by Europe PMC text mining. Sharing a sentence is not in itself a finding about the gene and the disease. The quoted sentences say what the papers report.
meningitis (2 papers, 2019 to 2022). A disorder characterized by acute inflammation of the meninges of the brain and/or spinal cord. "In an interesting parallel to this, common genetic variation at another ubiquitin-conjugating enzyme, UBE2U, has been shown to modify outcome in meningitis secondary to diverse pathogens in individuals of European ancestry." (PMID 35866869, 2022).
cataract (1 paper, 2021). Partial or complete opacity of the crystalline lens of one or both eyes that decreases visual acuity and eventually results in blindness. "In addition, we identify two potentially novel associations: LRP1 in early-onset drusen formation and UBE2U in a multi-system condition presenting with retinoschisis, cataracts, learning disabilities, and developmental delay." (PMID 33776059, 2021).
retinal disease (1 paper, 2021). "Our approach used WES to identify novel genes in IRDs and through this work we have identified two putatively novel associations in retinal disease: LRP1 in drusen formation and UBE2U in a novel syndrome." (PMID 33776059, 2021).
schizophrenia (1 paper, 2024). A major psychotic disorder characterized by abnormalities in the perception or expression of reality. "Interestingly, we found the increased expression of four ubiquitin-conjugating enzymes (E2) - UBED1, UBED3, UBEB, and UBE2U - in male schizophrenia patients." (PMID 39068467, 2024).
tumour (1 paper, 2024). "Hence, our endeavour revolves around corroborating whether the remarkably potent transcription factor, CREB3, within UBE2U+ tumour cells, exerts regulatory control over the unrestrained proliferation of GC cells." (PMID 38894657, 2024).
UBE2U also shares sentences with these, for which no sentence is quoted: developmental delay (1 paper); learning disabilities (1); pneumococcal meningitis (1); retinoschisis (1); RIDDLE syndrome (1).